GDF15 (growth differentiation factor 15)
Diseases named in the same sentence as GDF15 in open-access papers (continued):
Sharing a sentence is not in itself a finding about the gene and the disease.
cancer (continued). "Based on our previous results showing that GDF15 was markedly up regulated in the residual leukemic cells after chemotherapy and reports that GDF15 confers drug resistance to other cancer cells, we questioned whether CAFs in the BM could also play an important role by secreting GDF15." (PMID 27643489, 2016). "However, as the tumor advanced, these mice also developed more metastases, suggesting that MIC-1/GDF15 overexpression may have deleterious actions late in the course of cancer." (PMID 25695521, 2015). "Thus, GDF15 is discussed as a biomarker for cancer patients." (PMID 25823874, 2015). "However, whether MIC-1/GDF15 overexpression in cancer has a beneficial, harmful or mixed effect on disease outcome is difficult to determine from epidemiological studies alone." (PMID 25695521, 2015). "Therefore, GDF15 is discussed in the literature as a biomarker for various cancer types." (PMID 25823874, 2015). "Moreover, like other TGF-β family members, GDF15 might serve as a proapoptotic factor in early-stage cancers, while promoting tumor progression in advanced disease." (PMID 25490861, 2015). "GDF-15 is expressed by many cell types in response to oxidative stress and inflammation and seems to be involved in the regulation of apoptosis, cell proliferation and cellular repair, biological processes that are key components of cardiovascular and cancer pathobiology." (PMID 24312445, 2013). "In a recent phase 2, randomised, double-blind trial, 281 patients with advanced cancer (NSCLC, PDAC, and CRC) were screened for cancer cachexia (defined by Fearon’s criteria) and elevated serum GDF-15 levels (NCT05546476)." (PMID 41294666, 2025). "GDF‐15, a member of the transforming growth factor‐beta (TGF‐β) superfamily, is a stress‐responsive cytokine frequently elevated in various cancers, including BC." (PMID 41380167, 2025). "Collectively, our research indicates that TTN, GDF15, and MAPK14 can serve as prognostic biomarkers in female KIRC patients, offering prospects for enhanced treatment and patient outcomes in these cancers." (PMID 40854626, 2025). "Growth/Differentiation Factor 15 (GDF15) was reported to be highly elevated in PMMs and cancer cachexia." (PMID 39976232, 2025). "Since EpCAM is known to promote cancer progression through β-catenin and NF-κB signaling, we focused on investigating its interaction with NAG-1/GDF15." (PMID 40316530, 2025). "Conversely, GDF15, a member of the TGF‐β superfamily and derived from MP7, induced the aggregation of CAFs and NFs toward cancer cells through the TGFBR2 receptor, thereby promoting their transformation into the myCAFs subpopulation." (PMID 40292733, 2025). "Our study is the first to systematically evaluate GDF15 expression in LSCC using both protein and mRNA-level analyses, addressing a significant knowledge gap in biomarker research for this cancer type." (PMID 40725563, 2025). "Growth differentiation factor 15 (GDF-15), a TGF-β superfamily produced in large quantities by various cancer types, can disrupt the antitumor immune response." (PMID 40732268, 2025). "However, the general nonspecificity of GDF-15 may, in fact, enhance its value as a marker for bleeding events, which themselves are heterogeneous and arise from various causes in patients with cancer." (PMID 39967200, 2025). "Proteins such as GDF15, MERTK, MRP2, SMPD-1, GPNMB, GRN, and FSTL1, while less widely recognized, have emerging roles in cancer progression, immune modulation, and metabolic regulation." (PMID 40805206, 2025). "For mortality attributed to cancer, 28 proteins were statistically significant, with SERPINA3 showing the largest effect (2.79), alongside DDR1, LRG1, and GDF15 as the top contributors." (PMID 41270070, 2025).
cancer (continued). "However, extensive data on patients with AF and the small cancer patient cohort in the AVERT trial suggest that the association between GDF-15 and bleeding risk is at least as strong, if not stronger, in patients receiving anticoagulation compared with those not receiving anticoagulation." (PMID 39967200, 2025). "GDF15, belonging to the TGF‐β superfamily, impacts cancer progression by enhancing tumor growth, metastasis, and drug resistance through modulation of TGF‐β signaling pathways." (PMID 39083441, 2025). "Among these factors, growth differentiation factor 15 (GDF15), a stress-responsive cytokine, is upregulated in multiple cancers, including GBM, and correlates with poor prognosis and therapy resistance 26-29." (PMID 41281763, 2025). "Given that NAG-1/GDF15 inhibited PMA-induced protein synthesis, we examined various signaling pathways involved in cancer cell growth." (PMID 40316530, 2025). "To support their possible roles in crucial oncogenic mechanisms, we assessed the mutation frequency, copy number amplification, and copy number–expression correlation of STC2, MIF, CD74, CXCR4, GDF15, and TGFBR2 across several cancer types." (PMID 41502509, 2025). "The levels of growth differentiation factor 15 (GDF15), which belongs to the family of TGF-β, are upregulated during inflammatory conditions or cancer as compared to normal physiological conditions." (PMID 38571964, 2024). "Significantly higher levels of GDF-15 expression were observed in patients with CVD, COPD and cancer (p<0.0001, 0.0030 and <0.001 respectively) compared to severe cases without those conditions." (PMID 38686386, 2024). "We selected eight candidates (CST4, CCL20, CX3CL1, CXCL5, CXCL8, GDF15, CCL5 and MMP3) that play an important role in cancer pathogenesis for further study." (PMID 38385965, 2024). "Recent studies showed that the growth differentiation factor 15 (GDF15) played an important role in the regulation of metabolism, appetite, body weight control and anorexia–cachexia syndrome of cancer." (PMID 39700016, 2024). "In malignant tumors, the polarized M2 macrophages produce and secrete cytokines such as CCL18, CCL20, CCL22, IL10, TGFB1, and GDF15." (PMID 39272860, 2024). "Thus, GDF-15 may also influence cancer cachexia, like IL-6, through the AP network." (PMID 38824130, 2024). "Furthermore, while GDF15 offers protection by alleviating impaired mitochondrial function, its induction of the mitochondrial integrated stress response in papillary thyroid carcinoma patients can also contribute to cancer progression via the GDF15-STAT3 pathway." (PMID 39737171, 2024). "It is also noteworthy that metformin increases GDF15 and decreases TXNIP in cancer cells, an effect which has been suggested to contribute to metformin’s anticancer effects." (PMID 38255875, 2024). "In order to systematically analyze the role of GDF15 in cancer, we utilized TCGA PANCAN dataset and looked at the expression level of GDF15 mRNA across different types of tumors." (PMID 38082448, 2023). "Promising cardiac‐specific biomarkers in cancer‐induced cardiac cachexia models and cachectic cancer patients include factors from the TGF‐β family, such as GDF‐15, autophagy markers, such as Beclin‐1, and markers of protein synthesis, such as AKT and mTOR." (PMID 37654192, 2023). "To address that, we searched for correlations of GDF15 and BRD4 linear regression slopes upon treatment in NCI-60 cancer cell lines." (PMID 37495707, 2023).
cancer (continued). "Inhibition of GDF15–GFRAL signaling by monoclonal antibody 3P10 showed beneficial effects on lipid metabolism and reversed cancer cachexia in mice." (PMID 35994202, 2022). "Elevated Growth/differentiation factor 15 (GDF15) level in serum and increased GDF15 expression in cancer tissues are reported in patients with various cancers, and associated with the poor prognosis of the patients." (PMID 36105219, 2022). "Although GDF-15 has tumor suppressive effects, increased serum GDF-15 in cancer patients indicates advanced disease." (PMID 36008442, 2022). "In short, the GDF15–GFRAL axis controls body weight through central pathways (food intake) and peripheral pathways (lipid oxidation and muscular wasting), especially in cancer cachexia." (PMID 36105371, 2022). "GDF15 is a member of the TGF- β superfamily of growth factors as well, whose circulating levels are significantly increased in cancer pancreatic ductal adenocarcinoma." (PMID 36078078, 2022). "With increasing evidence verifying the expression of GFRAL is also in cancer tissues, clues of GFRAL-independent effects of GDF-15 are also accumulating." (PMID 35963873, 2022). "A therapeutic antagonistic monoclonal antibody, which targets GFRAL and inhibits RET signaling by preventing the GDF15-driven interaction of RET with GFRAL on the cell surface, successfully prevented cancer cachexia." (PMID 35379793, 2022). "GDF15 has protective role in obesity-related disease and NAFLD, whereas it showed detrimental role against age related muscle atrophy and cancer cachexia-related muscle atrophy." (PMID 36046792, 2022). "Among these genes, GDF-15 was upregulated in a lidocaine dose-dependent manner, suggesting that GDF-15 plays a significant role in lidocaine-induced growth suppression of cancer cell lines." (PMID 36008442, 2022). "The 3-h half-life of GDF-15 is prolonged in the circulation, and the serum levels of GDF-15 increase markedly in advanced cancer." (PMID 34150865, 2021). "The miR-216a expression levels retrieved from the OncoMir Cancer Database (OMCD) and the GDF15 accessed from GDS2609 of GEO database confirmed the findings." (PMID 34948431, 2021). "We also noticed that growth factors, including NOV, BMP4, MDK, GDF15, VEGFC, NTF3, and LIF, were previously reported to promote cancer development, especially in cancer metastasis in various cancers, including CRC." (PMID 34440086, 2021). "The Genomics of Drug Sensitivity in Cancer (GDSC) and Cancer Therapeutics Response Portal (CTRP) analysis identified that Gemcitabine acted as a precision treatment for COAD when GDF15 expression was low." (PMID 34948431, 2021). "S100A2, TGFA, MET, PCNA, SCD, GDF15, and PAI1 act as oncogenes by promoting cancer metastasis or proliferation 24-30." (PMID 34131400, 2021). "GDF-15 has also been shown to predict both the morbidity and mortality of CVD and cancer in apparently healthy older men." (PMID 32899694, 2020). "Similar to cancer and COPD, in PH models, GDF15 contributed to skeletal muscle atrophy through increased phosphorylation of TGFβ-activated kinase 1 (TAK1)." (PMID 33344478, 2020). "Among the proteins differentially present in cancer vs. control were six common to both local and metastatic PDAC: Up—GDF15, TIMP1, and IL1RL1; Down—CCL22, APP, and CLEC1B." (PMID 33334063, 2020). "Growth differentiation factor 15 (GDF-15; also known as macrophage inhibitory cytokine 1) has been recognized among the top interest cancer biomarkers." (PMID 33144847, 2020). "Previous studies have shown that GDF15 can promote EMT and metastasis in colorectal cancer and contribute to radioresistance and cancer stemness of head and neck cancer." (PMID 33062674, 2020). "If the concentrations of plasma IL6 and GDF15 exceed the critical value, positive feedback cycles of inter-BAT mutual activations would be created to induce cancer cachexia as a result of uncontrolled catabolism." (PMID 33182625, 2020).
cancer (continued). "A novel inflammatory cytokine, the Growth Differentiation Factor-15 (GDF-15), a member of the transforming growth factor beta family, has been found significantly elevated in cancer patients." (PMID 33396237, 2020). "Of note, our upstream analysis identified several TGF-beta superfamily of proteins such as MSTN, GDF11, GDF15, TGF-β suggesting their important roles in cancer and in cachexia, offering a window for therapeutic interventions." (PMID 33334063, 2020). "In a microarray-based study comparing 150 carcinomas from 10 anatomic sites of origin with 46 normal tissues derived from the corresponding tissues of tumor origin and other control non-transformed tissues, GDF-15 showed the highest level of tumor-associated (over)expression." (PMID 32508832, 2020). "GDF15 (also known as MIC-1, NAG-1, PLAB, PTGFB) is a cytokine of the TGF-β superfamily that is up-regulated in response to inflammation, cardiovascular disease, obesity, and cancer." (PMID 31861872, 2019). "Furthermore, several papers showed that GDF-15 may be involved in muscle wasting in a variety of patients including COPD, patients undergoing elective high-risk cardiothoracic surgery, intensive care unit (ICU) patients, and cancer patients." (PMID 31581569, 2019). "The results were consistent with previous reports showing that the circulating GDF-15 concentration was negatively correlated with the cross-sectional area of rectus femoris in COPD, ICU, and cancer patients." (PMID 31581569, 2019). "Expression of Growth/differentiation factor 15 (GDF-15), a member of the TGF-β family that plays a role in tissue regeneration and healing, is greatly enhanced in various types of cancer." (PMID 30646851, 2019). "Therefore, the role of GDF15 may vary from different cancer types." (PMID 29262584, 2017). "Thus, GDF15 may also be involved in DGC progression mediated by cancer-stromal interaction." (PMID 26892343, 2016). "Spontaneously developing cancers in transgenic mice often most closely conform to human cancers and all studies based on their use suggest that MIC-1/GDF15 is largely protective in early disease." (PMID 25695521, 2015). "The amount of MIC-1/GDF15 present in serum of cancer patients is, in part, dependent on the proportion of MIC-1/GDF15 localized to the tumor versus that diffusing into the circulation." (PMID 22952779, 2012). "Protein profiling of GDF15 expression was performed using HPA011191 on TMAs containing normal tissues from 140 different individuals, cancer tissues from 216 patients and 47 cell lines." (PMID 21468045, 2011). "Obviously, for both GDF15 and THBD, additional studies are necessary to elucidate their role in cancer biology and determine its potential clinical significance." (PMID 15900300, 2005). "GDF-15 is a member of the transforming growth factor-β (TGF-β) superfamily and is involved in several biological processes, including oxidative stress response, weight management, inflammation, and cancer progression." (PMID 41597417, 2026). "Furthermore, GDF15 binds to TGF-β receptors, leading to the phosphorylation of SMAD2/3 and SMAD1/5/8, which promotes the progression and cancer cells." (PMID 40144214, 2025). "GDF-15 plays a negative immunomodulatory role by impairing T-cell infiltration and promoting T-cell exhaustion, enabling cancer cells to escape immunity and resist immune checkpoint inhibitors (ICIs)." (PMID 41294666, 2025). "Our study confirms and expands these exploratory findings with robust data on bleeding in an unselected cohort of consecutive cancer patients, particularly as GDF-15 levels were not predictive of major bleeding in the placebo group of the AVERT trial." (PMID 39967200, 2025). "Pan-cancer immunotranscriptomic analyses revealed a negative correlation between GDF-15 mRNA expression levels and T-cell transcriptomic signatures in various solid cancer subtypes." (PMID 41294666, 2025).
cancer (continued). "They secrete TGF-β, leukemia inhibitory factor (LIF), growth arrest-specific protein 6 (GAS6), fibroblast growth factor 5 (FGF5), growth differentiation factor 15 (GDF15), and hepatocyte growth factor (HGF), which drive the invasive and proliferative behaviors in cancer cells." (PMID 40313969, 2025). "Supporting this hypothesis, recent work in an animal model of cancer demonstrated that neutralizing GDF-15 improved muscle function and physical performance, suggesting GDF-15 is a potential therapeutic target in myopathies." (PMID 38058222, 2025). "Findings of our study showed significant upregulation in GDF15 protein expression in both skeletal and cardiac muscle tissue of SED+T mice, but not WR+T counterparts, suggesting a unique physical activity-mediated muscle protection in cancer cachexia." (PMID 40558549, 2025). "One pilot study showed GDF15 elevation in newly diagnosed patients with cancer compared to healthy controls but fails to account for paediatric tumoral differences and unique molecular profiles compared to adults." (PMID 40019842, 2025). "Elevated circulating GDF-15 is not specific for cancer or CC, as levels can be influenced by inflammation, cardiovascular and renal dysfunction, aging, and exposure to various medications." (PMID 40868185, 2025). "Growth differentiation factor 15 (GDF15) is a stress-responsive cytokine within the transforming growth factor beta (TGF-β) superfamily, playing roles in inflammation, metabolism, and cancer." (PMID 40181460, 2025). "Growth differentiation factor 15 (GDF15), a protein implicated in various cancers, has not been thoroughly investigated in LSCC." (PMID 40725563, 2025). "GDF15 triggers the activity through its receptor Glial-derived neurotrophic factor-family receptor α-like (GFRAL) and mediates multiple downstream signaling cascades, which are involved in the progression of cancers." (PMID 40128491, 2025). "Currently, there are no approved antibody drugs specifically targeting GDF15 for cancer cachexia treatment." (PMID 39172988, 2024). "Currently, there are no approved antibody drugs specifically targeting GDF15 for the treatment of cancer cachexia; however, as an emerging target, several pharmaceutical companies have developed corresponding antibody drugs to address this condition." (PMID 39172988, 2024). "Several studies have examined the prognostic value of IL-6 in cancer therapy, yet its relationship with biomarkers such as GDF-15 has not been fully explored." (PMID 39766045, 2024). "In DOX-surviving proliferative cells, we found positively correlated gene pairs, for example, two senescent markers (GDF15 and CDKN1A R= 0.54) and anticorrelated gene pairs, for example, GDF15 and genes involved in cancer progression: CDC20 (R= -0.26) and BIRC5 (R= -0.17)." (PMID 39405604, 2024). "Growth differentiation factor 15 (GDF-15), a member of the transforming growth factor-beta (TGF-beta) superfamily, is increasingly recognized for its role in immune modulation and as a marker of cancer-related cachexia." (PMID 39766045, 2024). "Studies on the role of GDF15 in tumors are not uncommon, but the function of GDF15 in different cancer types is controversial." (PMID 38082448, 2023). "For example, BAX expression among cancer cells is lowest in upper aerodigestive lineages (UAD) and highest in fibroblast lineages; CDKN1A is lowest in blood and highest in fibroblasts; GDF15 is lowest in lymphocytes and highest in kidney; and MDM2 is lowest in thyroid lineages and highest in cervix." (PMID 36681780, 2023). "GDF15 stimulates the PI3K/AKT, ERK, and NF-κB signaling pathways in various cancers." (PMID 36769245, 2023). "Although increased plasma growth differentiation factor-15 (GDF15) levels have been reported in patients with various cancers, the predictive role of PD-1/PD-L1 inhibitors in advanced cancers remains unknown." (PMID 36472770, 2023).